MYCN (MYCN proto-oncogene, bHLH transcription factor)
Diseases named in the same sentence as MYCN in open-access papers (continued):
Sharing a sentence is not in itself a finding about the gene and the disease.
neuroblastoma (continued). "Therefore, combined ADC and T1 histogram analysis may help distinguish neuroblastoma subtypes with different biological behaviors, particularly those associated with MYCN amplification." (PMID 41228227, 2025). "Interestingly, MYCN amplification in neuroblastoma has showed association with 17q gain." (PMID 40365336, 2025). "Together, these findings underscore the dual role of MYCN in both driving aggressive tumor growth and modulating immune susceptibility, highlighting the potential use of glycosylation-related gene signatures as valuable predictive tools in neuroblastoma prognosis." (PMID 39860532, 2025). "Through a comprehensive analysis of the biological functions and pathogenic mechanisms of MYCN, this review aims to provide a theoretical basis for the development of new therapeutic strategies with MYCN amplification as a therapeutic target, especially for neuroblastoma." (PMID 41244073, 2025). "MYCN amplification is the most common genetic aberration associated with poor prognosis in neuroblastoma (NB) and is identified as the primary driver in a rare and aggressive subtype of retinoblastoma (RB)." (PMID 37975412, 2024). "MYCN amplification is an independent poor prognostic factor in patients with high-risk neuroblastoma (NB)." (PMID 38336749, 2024). "Moreover, MYCN is induced by IR and linked to radioresistance in neuroblastoma." (PMID 39107280, 2024). "Moreover, THZ1 induces apoptosis of MYCN-amplified cells and correlates with the downregulation of SE-associated genes, unlike MYCN-non-amplified cells, which evidences the selective vulnerability of MYCN-amplified neuroblastoma cells to this inhibitor." (PMID 38542080, 2024). "This mutational scenario was enriched in high-risk non-MYCN-amplified neuroblastomas, suggesting that the high number of CNAs and SVs found in this risk group might be caused by the portrayed HRR deficiency, which is in line with recent reports in other cancer types." (PMID 37868040, 2023). "MYCN amplification is an independent risk factor for poor prognosis in neuroblastoma (NB), but its protein product cannot be directly targeted because of protein structure." (PMID 36708875, 2023). "Moreover, in serum from children with International Neuroblastoma Staging System (INSS) stage 4 tumors (p < 0.0001), high-risk neuroblastoma (p < 0.0001), MYCN amplified neuroblastoma (p = 0.0088), and in children who died (p = 0.034) GD2 concentration was significantly higher." (PMID 36824365, 2023). "Furthermore, targeted inhibition of Aurora-A in high-risk neuroblastoma could emerge as a principal strategy aimed at breaking its highly oncogenic partnership with MYCN." (PMID 37414143, 2023). "Consequently, the DNA-replicative stress caused by ATRX mutations and MYCN amplification causes synthetic lethality in neuroblastoma, representing an uncommon instance in which the inactivation of a tumor-suppressor gene and activation of an oncogene are incompatible." (PMID 37190157, 2023). "Amplification of the MYCN oncogene is found in ~20% of neuroblastoma (NB) cases and correlates with high-risk disease and poor prognosis." (PMID 37175848, 2023). "With PNA BGA002, they targeted MYCN-amplified neuroblastoma (MNA–NB) cells, in which MYCN was associated with increased ROS, downregulated mitophagy, and a poor prognosis." (PMID 37896275, 2023). "In this regard, it is interesting that aberrantly high LMO3 expression levels appear to be frequent in neuroblastomas with MYCN gene amplification, which may explain the lack of association of the rs2168101 genotype with the risk of developing MYCN-amplified neuroblastomas." (PMID 37183825, 2023). "However, further in vitro experiments revealed that LIG4, the worse prognostic factors in MYCN-amplified neuroblastomas, might play complementary roles in DNA-PKcs deficiency." (PMID 37240360, 2023).
neuroblastoma (continued). "Moreover, studies have revealed significantly poorer outcomes in a subgroup of patients with stage 4S neuroblastoma characterized by MYCN amplification, chromosomal aberrations (1p loss of heterozygosity, 11q aberration, 17q gain), diploidy, and age of < 2 months at diagnosis." (PMID 37286818, 2023). "Amplification of the MYCN gene is one of the few indicators of poor prognosis in neuroblastoma, and MYCN amplification is common in individuals with high-risk NB, accounting for roughly 20% of primary NB." (PMID 37745860, 2023). "Based on the neuroblastoma data, this distinct property may also have implications beyond retinoblastoma and may be linked to the general biological features of pediatric cancers harboring MYCN amplification." (PMID 36245757, 2022). "We previously found highly expressed SNHG1 was associated with poor prognosis and MYCN status in neuroblastoma (NB)." (PMID 36130928, 2022). "In summary, PET-based intratumor heterogeneity could serve as a powerful and non-invasive approach to predict MYCN amplification and survival outcome in newly diagnosed neuroblastoma, providing a potential approach to refine the risk stratification in children with high-risk diseases." (PMID 36353561, 2022). "Neuroblastoma (NB) is a devastating malignancy threatening children’s health, and amplification of MYCN is associated with treatment failure and a poor outcome." (PMID 35242701, 2022). "Hence, it can be hypothesized that the transcriptional axis MYCN/TWIST1/DDR2/SNAIL1 could drive high-risk neuroblastoma tumor invasion and metastasis." (PMID 34716856, 2022). "Also, E2F1 and E2F3 were associated with MYCN amplification and age of neuroblastoma diagnosis." (PMID 35764946, 2022). "Owing to it association with MYCN, it is reasonable to speculate that bub1 is also involved in the development of neuroblastoma and may be used to guide targeted immunotherapy against neuroblastoma." (PMID 36237324, 2022). "Among them, MYCN amplification accounts for 20% of primary neuroblastoma and it is closely associated with advanced NB and resistance to treatment." (PMID 36187481, 2022). "Thus, targeting of MYCN’s epigenetic network may prove an effective therapeutic avenue for high-risk neuroblastoma." (PMID 33968920, 2021). "MYCN amplification (MNA) is established as a major driver of Neuroblastoma (NB) (characterizing 50% of the high-risk group)." (PMID 33718189, 2021). "Therefore, profiling the TMEs of MYCN-NA tumors may identify biomarkers to improve risk stratification and development of novel treatment approaches for patients with high-risk neuroblastoma." (PMID 35464627, 2021). "Therefore, in non-MYCN amplified neuroblastomas, the loss of MRE11 with the accompanying 11q deletion may contribute to poor prognosis as a consequence of their irregular DNA repair." (PMID 34069817, 2021). "Long term survival of high-risk neuroblastoma (HR-NB) (metastatic disease over 1 year of age- or MYCN-amplified disease) currently remains less than 50% at 5 years despite intensive high-dose multimodal treatment." (PMID 32354033, 2020). "Neuroblastoma (NB) is the most common extracranial solid tumor in infants and children, with amplification of the oncogene MYCN being a hallmark of high‐risk disease and poor prognosis." (PMID 33034426, 2020). "As a driver of neuroblastoma, associated with poor outcome, MYCN is an important potential therapeutic target for high-risk NB." (PMID 32577161, 2020). "Analysis of miR-145 expression levels in 86 primary diagnostic neuroblastoma samples revealed significantly lower expression of miR-145 (based on median expression) in patients with known higher risk prognostic factors including MYCN amplification (MNA) and INSS Stage 4 disease." (PMID 32083506, 2020).
neuroblastoma (continued). "Further exploration of this novel association may potentially improve prognostication and risk stratification of children with neuroblastoma by leveraging germline genetic risk variants and may reveal therapeutic targets for aggressive MYCN‐amplified neuroblastoma." (PMID 32945147, 2020). "Interestingly, SF-1 has also been mentioned in association with MYCN and neuroblastoma progression." (PMID 33396509, 2020). "One possible mechanism through which ALK mutations may render neuroblastoma more aggressive is through increased MYCN activity resulting from PI3K-directed activation of ERK5 transcription levels or inhibiting GSK3ß-mediated repression of MYCN protein degradation." (PMID 31937834, 2020). "Furthermore, the P44L mutation is associated with increased mRNA levels of MYCN in neuroblastoma." (PMID 33614505, 2020). "Notably, MYCN amplification—the powerful adverse prognostic factor occurring in 16% to 25% of NB patients—causes chemotherapy resistance, especially in advanced stage neuroblastomas." (PMID 32455831, 2020). "The International Neuroblastoma Staging Series (INSS) classifies NB patients by risk level, tumor location and dissemination, and MYCN amplification." (PMID 31635049, 2019). "Moreover, Oct4 seems to be linked with NBT neovascularization when co-expressed with Tenascin C in perivascular neuroblastic cells, and other studies have reported that Oct4 is also associated with MYCN amplification and stages 3 and 4 of the International Neuroblastoma Staging System." (PMID 30606139, 2019). "Furthermore, high-risk neuroblastoma can be classified into different biological subsets based on molecular characterization including MYCN amplification status, c-MYC expression, ALK and ATRX mutations, TERT rearrangements and alternative mechanisms of telomere lengthening (ALT)." (PMID 28924803, 2018). "However, unlike in bone marrow stromal cells and patellar tendon stem cells where KGN also increases proliferation, KGN induced a loss of viability in MYCN-amplified neuroblastoma cells, showing therapeutic potential, an effect which was further enhanced by co-treatment with RA." (PMID 28187790, 2017). "Furthermore, we analyzed whether CHERP expression levels were associated with MYCN expression in neuroblastoma patients." (PMID 29113358, 2017). "We detected low-level CD9 expression in primary neuroblastomas that correlated with metastasized high-risk disease, low probability of patient survival and established clinical and molecular markers for unfavorable disease including MYCN amplification in the tumor." (PMID 27572323, 2016). "Besides MYCN amplification (the hallmark of high-risk neuroblastoma), chromosomal alterations—specifically copy number variants at 1p, 11p, 2p, 3p, 4p, 6p, 6q, 1q, 11q and 17q—have been identified using array-CGH and single nucleotide polymorphism (SNP) analyses." (PMID 28035989, 2016). "We also show that the very aggressive growth properties of MYCN-induced neuroblastomas with loss of nf1 are due to aberrant activation of RAS signaling, because the increased penetrance and rapid growth could be suppressed by overexpressing the intact NF1 GRD domain." (PMID 27130733, 2016). "MYCN amplification (MNA) in neuroblastoma (NB) generally associates with an aggressive tumor behavior and detection of MNA leads to an automatic upstaging of the tumor in non‐stage 1 tumors." (PMID 26910568, 2016). "Although MYCN amplification and consequent overexpression has been established as a key driver of malignancy in MYCN-amplified high-risk neuroblastoma, the exact mechanisms by which MYCN contributes to the aggressive phenotype of neuroblastoma remain largely unknown." (PMID 27448979, 2016). "Indeed, a recent publication from Adinolfi’s group nicely demonstrated that P2X7R triggers PI3K/Akt activation in neuroblastoma cell lines and derived tumors, thus affecting the main downstream effectors implicated in neuroblastoma progression: GSK3β/MYCN and HIFα/VEGF pathways." (PMID 26687764, 2015).
neuroblastoma (continued). "There is a clear need to more deeply interrogate the role of the ALKF1174L mutation on vascular morphogenesis and architecture, which may be a major determinant of impaired drug delivery and a contributing factor to the poor prognosis of children with ALKF1174L-mutated MYCN-amplified neuroblastoma." (PMID 24667968, 2014). "Thus, MYCN might have enhanced S6K phosphorylation by activating the mTOR pathway in neuroblastomas caused in the double transgenic mice." (PMID 24391509, 2014). "In addition, FISH techniques to rapidly determine the MYCN status at the cellular level and enabling the detection of intratumoral MYCN heterogeneity are expected to remain in use in the diagnostic work up of neuroblastomas." (PMID 25161957, 2014). "Analysis of miR-497 expression levels in 143 primary diagnostic neuroblastoma samples revealed significantly lower expression of miR-497 (based on median expression) in patients with known higher risk prognostic factors including MYCN amplification (MNA) and INSS Stage 4 disease." (PMID 23531080, 2013). "All-trans-retinoic acid (ATRA) causes some neuroblastoma (NB) cell lines to undergo differentiation and leads to a significant decrease in the oncogenic transcription factor MYCN." (PMID 23565812, 2013). "An important pathology of the sympathetic peripheral nervous system is neuroblastoma (NB), where amplification of MYCN is strongly associated with poor prognosis." (PMID 23675538, 2013). "Interestingly, a ChIP-chip array study of MYCN/c-MYC target genes in neuroblastoma demonstrated that distinct MYCN/c-MYC target gene expression was associated with overall survival, and independent of well-established markers such as MYCN amplification, disease stage, and age at diagnosis." (PMID 23226679, 2012). "However, although MYCN has been associated with high-risk tumors, more than 60% of patients with aggressive disease do not exhibit this mutation, suggesting that other genetic mechanisms are involved in the pathophysiology of neuroblastoma." (PMID 21892309, 2008). "This review examines current therapeutic strategies and resistance mechanisms in MYCN-amplified neuroblastoma, while introducing emerging approaches utilizing exosomes as precision drug delivery systems." (PMID 41750126, 2026). "Twenty-eight (43%) patients had refractory neuroblastoma, and 37 (57%) had relapsed neuroblastoma; 51 (78.5%) had measurable disease, and 14 (21.5%) had evaluable disease; 19 (29%) had MYCN amplification; 24 (37%) had received previous anti-GD2." (PMID 41385757, 2026). "RP-1664 combined with GD2-directed chemoimmunotherapy resulted in maintained complete responses in 6/9 mice with established MYCN-driven murine neuroblastomas." (PMID 42288516, 2026). "RP-1664 monotherapy showed robust anti-tumor activity in 14/15 human neuroblastoma-derived xenograft models, and significantly extended survival in a transgenic MYCN-driven murine model of neuroblastoma." (PMID 42288516, 2026). "The expressions of BMP7 were higher in neuroblastoma patients with MYCN amplification or age ≥ 18months or in stage 4 neuroblastoma." (PMID 41632777, 2026). "By integrating knowledge of MYCN biology, molecular structures and chemical biology, these approaches provide promising routes towards targeted therapies for MYCN-driven neuroblastoma." (PMID 42233780, 2026). "We confirmed the association with MYCN and identified the RUVBL genes as independent prognostic biomarkers in human primary neuroblastoma data." (PMID 41940329, 2026). "In MYCN-amplified neuroblastoma, endogenous serine biosynthesis circumvents dependency on exogenous serine/glycine, preventing nucleotide pool collapse during deprivation." (PMID 41486146, 2026). "The relatively low incidence of neuroblastoma (11–13 cases per million children annually) and the limited frequency of MYCN amplification (~20% of cases) hinder large-scale clinical radiologic–pathologic studies." (PMID 41228227, 2025).
neuroblastoma (continued). "Here, we demonstrate that induction of high levels of HIF2α in MYCN-amplified neuroblastoma cells results in a rapid and profound reduction of the oncoprotein MYCN." (PMID 41118218, 2025). "Vasoactive intestinal peptide (VIP) significantly reduces MYCN expression in neuroblastoma cells (SH-SY5Y/IMR-32) and exhibits a synergistic inhibitory effect when combined with RA." (PMID 41244073, 2025). "MYC family is composed of three closely related genes, MYC (encoding Cellular-MYC), MYCN (encoding Neural-MYC), and MYCL (encoding Lung-MYC), identified in epithelial cells, neuroblastoma, and small cell lung cancer, respectively." (PMID 40362259, 2025). "The expression of another multidrug resistance gene, MRP4, also correlates with MYCN amplification in neuroblastoma." (PMID 39802403, 2025). "In pre-clinical studies, neuroblastoma with MYCN amplification has been shown to be generally sensitive to RA." (PMID 41380652, 2025). "Conversely, ncRNA MYCNOS was shown to be important in recruiting CTCF to the MYCN promoter in neuroblastoma cell lines, whereas eRNAs recruit CTCF to the boundary of the INK4a/ARF TAD in HeLa cells." (PMID 41296854, 2025). "Adoption of the mouse hospital and co-clinical concept, incorporating the use of GEM models such as the Th-MYCN mouse, is positively impacting on neuroblastoma translational research." (PMID 40359728, 2025). "For instance, diphenyleneiodonium demonstrates significant anti-tumor activity in MYCN-amplified neuroblastoma by targeting MYCN-induced mitochondrial alterations and ROS production, thereby inducing apoptosis and suppressing tumor growth." (PMID 41209000, 2025). "Consistent with our observations in MYCN-amplified neuroblastoma cells, the cytotoxic effects of Cas9D10A targeting an amplified locus were significantly reduced at many doses in the presence of PARP inhibitors or calpastatin." (PMID 40456709, 2025). "The reduction in immune-related gene expression aligns with previous reports indicating that immune evasion plays a key role in the aggressive behavior of MYCN-driven neuroblastoma." (PMID 39860532, 2025). "This study demonstrated that inhibiting G6PD with 6-AN enhanced the cytotoxic effect of 5-ALA-mediated PDT against MYCN-amplified neuroblastoma cells, a subtype often resistant to the standard treatments." (PMID 41291487, 2025). "Transcription factor activator protein 4 (TFAP4) is a key effector of MYCN amplification in neuroblastoma." (PMID 41244073, 2025). "Our preliminary studies indicate that these general DNA binding patterns are also conserved in the case of MYCN, the expression of which is largely confined to cell lines derived from neuroblastomas and a limited number of other cancers." (PMID 40443286, 2025). "Our findings show that high levels of HIF2α in neuroblastoma, leads to drastically reduced MYCN protein levels, cell cycle exit, and noradrenergic cell differentiation." (PMID 41118218, 2025). "An alternative strategy to lower MYCN levels involves targeting cyclin-dependent kinase 7 (CDK7) to interfere with the transcription of amplified MYCN in neuroblastoma cells." (PMID 40365336, 2025). "This immune exclusion is particularly pronounced in MYCN-amplified tumours (~25% of neuroblastomas), which exhibit transcriptional repression of interferon-stimulated genes, impaired antigen presentation, and reduced infiltration of CD8+ T cells and NK cells." (PMID 41366257, 2025). "To examine which polyamine transporters play a role in basal and DFMO‐induced polyamine uptake, we started by confirming our earlier discovery that SLC3A2 contributes to polyamine uptake in MYCN‐amplified neuroblastoma cells." (PMID 39981745, 2025). "Inhibition of the aldehyde dehydrogenase 18 family member A1-MYCN positive feedback loop attenuates the growth of MYCN-amplified neuroblastoma." (PMID 39802403, 2025).